PFKM (phosphofructokinase, muscle)
Diseases named in the same sentence as PFKM in open-access papers (continued):
Sharing a sentence is not in itself a finding about the gene and the disease.
tongue cancer (2 papers, 2021 to 2023). A malignant neoplasm affecting the tongue. "The results of log-rank test demonstrated that PGK1, CYP19A1, PFKM, and ZC3H12D were associated with the OS in tongue cancer patients." (PMID 33758601, 2021). "PGK1, SLC20A1, LEPR, CYP19A1, ZC3H12D, and PFKM were found to be independent predictors in tongue cancer." (PMID 33758601, 2021). "Previous studies have reported that the expression of LEPR 42, PFKM 43, 44, PGK1 45, 46, CYP19A1 47, 48, SLC20A1 49, and ZC3H12D 50 were associated with tumorigenesis and progression in various tumor types, which support the further identification and exploring in tongue cancer." (PMID 33758601, 2021). "Therefore, in the next step, we performed quantitative real-time PCR analyses of PFKM, PKM2, and LDHA gene expression in tongue cancer cells to validate these hypotheses." (PMID 38132445, 2023).
atrial fibrillation (1 paper, 2025). A disorder characterized by an electrocardiographic finding of a supraventricular arrhythmia characterized by the replacement of consistent P waves by rapid oscillations or fibrillatory waves that vary in size, shape and timing and are accompanied by an irregular ventricular response. "A recent study indicated that PFKM is a key enzyme for glycolytic activation and it accelerates cardiac fibroblasts and thus causes atrial fibrillation." (PMID 40943454, 2025).
bipolar disorder (1 paper, 2024). A disorder of the brain that causes unusual shifts in mood, energy, activity levels and the ability to carry out day-to-day tasks. "In bipolar disorder, most glycolytic genes were downregulated, which included PFKM, PFKP, and PFKL, providing support for decreased glycolytic flux, but the magnitude of gene expression change was greater among the upregulated genes." (PMID 39125835, 2024).
glucose metabolism disorders (1 paper, 2022). "Given that the proteins PFKM, GAPDH, ACO2, and MDH2 have rate-limiting effects on aerobic oxidative metabolism, the decreased expression is consistent with the results of glucose metabolism disorders in diabetic patients." (PMID 36187097, 2022).
heart failure (1 paper, 2025). Inability of the heart to pump blood at an adequate rate to meet tissue metabolic requirements. "PFKM, a muscle-specific phosphofructokinase, catalyzes the phosphorylation of fructose-6-phosphate and is critically involved in cardiovascular diseases; however, its mechanisms in glycolysis and heart failure warrant further investigation." (PMID 40244284, 2025).
hypertrophic cardiomyopathy (1 paper, 2021). A condition in which the myocardium is hypertrophied without an obvious cause. "In addition, the expression of muscle fiber genes (MYH, MYL, and TNNI) and glycogen metabolism-related genes (PKM, PFKM, and PYGM) decreased, indicating that the massive accumulation of TTX has an impact on the hypertrophic cardiomyopathy pathway and cardiac muscle contraction pathway." (PMID 34822510, 2021).
kidney cancer (1 paper, 2016). Primary or metastatic malignant neoplasm involving the kidney. "Knockdown of PFKP, but not PFKL or PFKM, inhibited kidney cancer cell growth and induced apoptosis and cell cycle arrest." (PMID 27049827, 2016).
lung squamous cell carcinoma (1 paper, 2019). "PFKM has mutations associated with survival outcomes in lung squamous cell carcinoma." (PMID 30704450, 2019).
lymphoma (1 paper, 2023). A malignant (clonal) proliferation of B- lymphocytes or T- lymphocytes which involves the lymph nodes, bone marrow and/or extranodal sites. "There were also significant haplotypes that had SNPs spanning CCNT1 (5 SNP haplotype) and PFKM (4 SNP haplotype), both of which were more common in lymphoma cases (13–19%) compared to controls (13%)." (PMID 37756103, 2023).
osteoarthritis (1 paper, 2021). A noninflammatory degenerative joint disease occurring chiefly in older persons, characterized by degeneration of the articular cartilage, hypertrophy of bone at the margins and changes in the synovial membrane. "Several of these SNVs, rs3771501 (TGFA), rs3993110 (TEAD1/DKK3), rs72979233 (CHRDL2), and rs7967762 (PFKM/WNT10B), are associated with multiple osteoarthritis joint sites." (PMID 34450027, 2021).
psoriasis (1 paper, 2023). An autoimmune condition characterized by red, well-delineated plaques with silvery scales that are usually on the extensor surfaces and scalp. "RT‒qPCR results showed that KCs from psoriasis patients expressed higher mRNA levels of glycolytic transporters (GLUT1) and glycolytic enzymes (PFKM, LDHA, HK2, PKM2, ENO1 and PGK1) than those from healthy skin." (PMID 37497003, 2023). "Consistently, RT‒qPCR results showed that K17 KO also downregulated the mRNA levels of the proliferation markers K17, K16, PCNA, Cyclin D1 and key enzymes (GLUT1, PFKM, LDHA, HK2, PKM2, ENO1 and PGK1) in the IMQ-induced psoriasis-like model." (PMID 37497003, 2023). "Moreover, Ki67 expression and the mRNA levels of proliferation markers K17, K16, PCNA, Cyclin D1 and key enzymes (GLUT1, PFKM, LDHA, HK2, PKM2, ENO1 and PGK1) were also decreased in epidermal KCs of the IMQ-induced psoriasis-like model with local application of BI-D1870." (PMID 37497003, 2023).
tongue tumor (1 paper, 2021). "In our study, we did find the abnormally upregulation of LEPR, PFKM and PGK1 in tongue tumor patients and their upregulation are related to patients' poor overall survivals." (PMID 33758601, 2021).
cancer (122 papers, 2010 to 2025). A tumor composed of atypical neoplastic, often pleomorphic cells that invade other tissues. "PFK1 exists in three isoforms: PFKM, PFKL, and PFKP, with PFKM, encoded by the PFKM gene, playing a crucial role in muscle glycolysis and gaining recognition for its role in cancer progression." (PMID 40149892, 2025). "PFKM expression levels have also been associated with cancer development and metastasis, LDHB catalyzes the interconversion of pyruvate and lactate." (PMID 37601754, 2023). "Out of the three isoforms, the PFKM is a crucial regulatory target encoded by the PFKM (phosphofructokinase muscle) gene, as it serves as an activator of muscle glycolysis, which is critical for cancer dissemination." (PMID 35328104, 2022). "The PFKM-C351S mutation decreased the proliferation rate of cultured cancer cells, and reduced tumor growth and metastasis in the mouse xenograft model." (PMID 33859186, 2021). "PFKM is part of the glycolysis pathway, and posttranslational modifications of the enzyme and silencing by miRNA can promote cancer cell proliferation or adaptation to metabolic stress." (PMID 37756103, 2023). "Based on the TCGA data, we checked the transcript expression level of isoenzymes which are important for cancer cells, i.e., PFKM, PKM2, and LDHA, among HNSCC patients." (PMID 38132445, 2023). "A significant 4 SNP haplotype spanned the cancer pathway gene PFKM (phosphofructokinase, muscle), and homozygosity for this haplotype was more common in cases (19%) compared to carriers (7%) and controls (3%)." (PMID 37756103, 2023). "Among the phosphoproteins, we validated four enzymes associated with cancer and present only in sEVs isolated from MCF7 and MDA-MB-231 cell lines: ATP citrate lyase (ACLY), phosphofructokinase-M (PFKM), sirtuin-1 (SIRT1), and sirtuin-6 (SIRT6)." (PMID 35203617, 2022). "Expression levels of phosphofructokinase-M (PFKM) are closely related to the occurrence and development of malignant tumors." (PMID 35203617, 2022). "Our findings indicated that S-nitrosylated PFKM enhanced the stability of PFKM active tetramer for the tolerance of a high level of ATP and citrate in cancer cells." (PMID 33859186, 2021). "The PFKP isoform, which was induced in MKL1 ΔN200 cells, frequently prevails over PFKM or PFKL in human cancer cells and in the EMT." (PMID 32699630, 2020). "For instance, in Glycolysis/ Gluconeogenesis and Biosynthesis of amino acids pathways, lysine 131 (K131) site of PGK1, K322 and K13 sites of ALDOA, K215 and K194 sites of GAPDH, K89 site of ENO1, K678 site of PFKM were hyper-lactylated in cancer cells and tissues." (PMID 40849487, 2025). "Additionally, cancer metabolism-related genes, including PFKM, IDH3G, PYCR1, and BCAT1, were strongly elevated in expression in response to increased LINC00473 levels." (PMID 38512964, 2024). "Moreover, our study shows that NAT10 functions as a cancer-promoting molecule by targeting the glycolysis genes PFKM and LDHA directly or indirectly through acetylation in mRNA to reduce glycolysis breakdown and inhibit tumorigenesis." (PMID 38233839, 2024). "Moreover, an in silico study reported PFKM as a potential therapeutic target for cancer and aerobic glycolysis." (PMID 35328104, 2022). "Thus, strategy that disrupts the regulatory effect of ZEB1 on PFKM should be developed as a treatment to HCC and other cancers with excessive expression of PFKM driven by ZEB1." (PMID 33897890, 2021). "S-nitrosation of PFKM and cellular respiration inhibition may work together for the endogenous NO regulation on the metabolism switch of cancer." (PMID 33859186, 2021). "So we investigated the connection of NOS1 with PFKM related to cancer cell proliferation." (PMID 33859186, 2021). "Changing the level of miR-320a regulated the expression of PFKm through the 3′UTR and influenced glycolysis, thereby affecting the Warburg effect in cancer cells." (PMID 38385979, 2024).
cancer (continued). "While PFKL and PFKM are enriched in liver and muscle, respectively, the third isoform, PFKP, is mainly expressed in platelet and also elevated in most human cancer cells." (PMID 37222403, 2023). "Conclusively, collective expression of all three rate limiting glycolytic genes (HK2, PFKM, and PKM2) as novel cancer metabolic biomarkers can be beneficial for predicting disease aggressiveness and diagnosis." (PMID 35328104, 2022). "In this study, statistically significant overexpression of glycolytic genes HK2, PFKM, and PKM2 was observed in advanced cancer stages." (PMID 35328104, 2022). "The results demonstrate that the specific activity of PFKM in BC cancer cell lines was not statistically different from the non-cancerous cell line." (PMID 35203617, 2022). "Although these metabolic genes were not correlated with age in several cancer cohorts, a statistically significant association of HK2 and PFKM gene overexpression with age was observed in our data." (PMID 35328104, 2022). "Studies have demonstrated that the expression of PFK-1 in cancer cells is often markedly elevated and that the compositions of PFK isozymes are also frequently altered with PFKL and PFKP typically being expressed at higher levels in cancer cells compared with PFKM." (PMID 38388430, 2024). "Therefore, PFKP, rather than PFKM and PFKL, is thought to be strongly linked to cancer growth, survival, and metastasis, and could be used as a marker for poor prognosis in cancer." (PMID 36276846, 2022). "The protein level of PFKP was consistently higher in 18 ccRCC samples compared with their adjacent non-malignant kidney tissues, while PFKM and PFKL proteins show comparable levels between normal and cancer groups." (PMID 27049827, 2016).
tumor (101 papers, 2010 to 2026). "Our findings reveal a novel mechanism through which USP7 senses fructose-2,6-bisphosphate levels to promote PFKM nuclear translocation, thereby sustaining tumor cell survival under nutrient deficiency by activating FAO." (PMID 41818193, 2026). "PFKM-C351S mutation reduced the size and weight of tumors compared to those of PFKM-WT tumor, and NOS1 promotion of tumor reduced by PFKM-C351S mutation." (PMID 33859186, 2021). "Interestingly, PFKM was significantly associated with tumor differentiation." (PMID 35328104, 2022). "Mechanistically, the levels of fructose-2,6-bisphosphate (F-2,6-BP) are decreased in tumor cells upon glucose deficiency, which enhances the interaction between ubiquitin carboxyl-terminal hydrolase 7 (USP7) and PFKM." (PMID 41818193, 2026). "Nonetheless, the exact role of PFKM in mediating cell survival within an acidic tumor microenvironment requires further investigation." (PMID 40149892, 2025). "PFKM, a rate-limiting enzyme in the glycolytic pathway, directly affects the Warburg effect in tumor cells." (PMID 39990656, 2025). "FTO, C-Jun and PFKM were individually detected using WB analysis in transgenic mouse primary tumor cells." (PMID 41184232, 2025). "IHC and IF staining also revealed that FTO deletion decreased C-Jun and PFKM expression in tumor tissues and MDO." (PMID 41184232, 2025). "We suggest that future studies should include longitudinal analyses of tumor tissue with these variants (in GPD1, PLKR, and PFKM) to understand their clonal evolution and the possible action as tumor driver progression." (PMID 39684297, 2024). "Gao discovered that nitric oxide synthase stabilizes the tetramer structure of PFKM through S-nitrosylation, promoting cancer cell proliferation and tumor growth by inducing glycolysis while reducing macrophage infiltration in the tumor microenvironment." (PMID 38577616, 2024). "Like PFKM and GPD1, PKLR also has a variant with a VAF above 0.5, indicating a potential relationship with the initial stages of tumor formation and possible glycolytic dysfunction." (PMID 39684297, 2024). "The inhibition of 2,6-2-fructose production decreases PFKM activity, which results in the inhibition of the growth of tumor cells." (PMID 35203617, 2022). "For several tumor types, the main activator of glycolysis is PFKM, and inhibition of this enzyme significantly reduces the growth and invasion of tumor cells." (PMID 30967137, 2019). "Nuclear PFKM interacts with c-MYC, which upregulates the expression of carnitine o-palmitoyltransferase 1 muscle isoform (CPT1B) to activate FAO, thereby sustaining tumor cell survival upon glucose deficiency." (PMID 41818193, 2026). "In addition, immunohistochemical staining and Western blot analysis further confirmed the inhibitory effect of CQ on the expression of CHKA and PFKM proteins in tumor tissues." (PMID 39990656, 2025). "Targeting ASIC1 or PFKM may represent a novel therapeutic strategy for disrupting tumor adaptation in liver malignancies." (PMID 40149892, 2025). "In addition, anti-C5aR1 Ab reduced PFKM ubiquitination in peritoneal macrophages from tumor-bearing mice, suggesting that upon C5aR1 inhibition or C5aR1 deletion, PFKM stabilization mediated by AKT2 activation was required for the M1 phenotype." (PMID 38331868, 2024). "The genes PFKP, PFKM, and PGK1 were associated with oncogenes that could reinforce the Warburg effect and tumor progression." (PMID 39684297, 2024). "Moreover, a positive correlation between glycolytic genes (HK2, PFKM, and PKM2) and a high Ki67 index was also observed, which is indicative of their association with cell proliferation and tumor aggressiveness." (PMID 35328104, 2022). "S-nitrosylation of PFKM may participate in the formation of glycosome in tumor metabolism alteration." (PMID 33859186, 2021). "Therefore, the enhancement of intracellular glucose metabolism by S-nitrosation of PFKM contributes to cellular proliferation and tumor metastasis." (PMID 33859186, 2021).
tumor (continued). "A glucose metabolism advantage drives NSUN2 upregulation in tumor cells, which stabilizes key glycolytic gene transcripts (GLUT1, HK2, PFKM) via mRNA methylation, enhancing tumor cells’ competitive advantage in glucose uptake." (PMID 41256859, 2025). "Mechanistically, glucose metabolic dominance triggers NSUN2 upregulation in tumor cells, where this functional RNA methyltransferase stabilizes key glycolytic transcripts (GLUT1, HK2, PFKM) through mRNA methylation." (PMID 40765828, 2025). "To verify the regulatory mechanism of the FTO/C-Jun/PFKM axis, we further executed C-Jun blocking experiments in KPC/FKPC primary tumor cells." (PMID 41184232, 2025). "The PFK1 type comprises three different subtypes: PFKP (platelet type), PFKM (muscle type), and PFKL (liver type); in addition, PFK1 activity is increased in tumor cells compared with normal tissues." (PMID 37190313, 2023). "Protein expressions of HK2, PFKM and PKM were found to be high in tumor tissues with cytoplasmic localization." (PMID 35328104, 2022). "Dysregulation of key metabolic genes, namely, HK2, PFKM, and PKM2, has the potential to disrupt glycolytic metabolism and remove additional barriers against tumor progression." (PMID 35328104, 2022). "Four enzymes from glycolysis were included: hexokinase (HK1), phosphoglucose isomerase (PGI), phosphofructokinase (PFKM), pyruvate kinase (PKM2, the major isoform in tumours) and lactate dehydrogenase (LDHA)." (PMID 30655616, 2019). "Additionally, increased NAT10 expression promotes glycolysis in tumor cells by stabilizing YTHDC1, PFKM, and LDHA mRNA, thus providing essential energy support for tumor growth." (PMID 39897026, 2025). "Interestingly, the rate-limiting enzyme-coding genes in the glycolysis pathway showed inconsistent expression pattern in tumor cells compared with normal: HK3 and PFKP were overexpressed, while PFKM was downregulated." (PMID 37553601, 2023). "Moreover, consistent with the in vitro experiments, PFKM-C351S reduced the content of S-nitrosated PFKM and the activity of PFK1 in SKOV3 tumor extracts." (PMID 33859186, 2021). "Moreover, the high expression of HK1, PFKM, and GAPDH genes correlated with the tumor degree of malignancy." (PMID 34573317, 2021). "Especially, the mRNA expressions of PFKM and LDHA were significantly reduced in both DLD-1 and LoVo cell lines, suggesting that melatonin attenuated tumor growth via regulating the re-programming of tumor metabolism." (PMID 34671196, 2021). "Moreover, the results of this study showed that after treatment with andrographolide, the expression levels of the glycolysis-related proteins HK2, PKM2, PFKM, and LDHA in 8505C and CAL62 thyroid cells decreased, further proving that andrographolide can inhibit glycolysis in ATC tumor cells." (PMID 34335811, 2021). "We also found that mRNA levels of PFKM were similar in ccRCC and non-malignant samples while PFKL was slightly up-regulated in tumor samples." (PMID 27049827, 2016).
infection (16 papers, 2013 to 2025). The state of being infected such as from the introduction of a foreign agent such as serum, vaccine, antigenic substance or organism. "The global network notably recognizes six proteins (EPHA2, FBL, PFKM, PSMA5, SSR1, and TFRC) for their involvement in the infection of cells (p: 9.58 × 10− 4)." (PMID 31159726, 2019).
cardiovascular diseases (4 papers, 2022 to 2025). "We also analyzed the expression of phosphofructokinase, muscle isoform (PFKM), which catalyzes the rate-limiting step of glycolysis and plays an important role in cardiovascular diseases." (PMID 40869358, 2025). "PFKM (Phosphofructokinase, Muscle), catalyzing the phosphorylation of fructose-6-phosphate, plays a very important role in cardiovascular diseases." (PMID 35804014, 2022). "Studies also indicate that PFKM plays a very important role in cardiovascular diseases." (PMID 35804014, 2022). "PFKM also plays a very important role in cardiovascular diseases." (PMID 35804014, 2022).